PRMT3 (protein arginine methyltransferase 3)
Description:
Protein-arginine N-methyltransferase that catalyzes both the monomethylation and asymmetric dimethylation of the guanidino nitrogens of arginine residues in target proteins, and therefore falls into the group of type I methyltransferases. Catalyzes the asymmetric arginine dimethylation at multiple sites in the Arg/Gly-rich region of small ribosomal subunit protein uS5/RPS2. Also appears to methylate other ribosomal proteins (By similarity). May regulate retinoic acid synthesis and signaling by inhibiting ALDH1A1 retinal dehydrogenase activity. Contributes to methylation of histone H4 'Arg-3', a specific tag for epigenetic transcriptional activation. Mediates asymmetric arginine dimethylation of histone H4 'Arg-3' (H4R3me2a) in the promoter region of miRNA miR-3648, to promote its transcription and osteogenesis.
Synonyms: HRMT1L3
Tractability: Small molecule: a structure with a bound ligand is known; a high-quality ligand is known; it belongs to a druggable protein family. PROTAC: ubiquitination databases record sites on it; its protein half-life has been measured; a small molecule that binds it is known.
Target class: Epigenetic regulator; Protein arginine methyltransferase; Writer; Protein methyltransferase
Chemical probes: MS023 (high quality), SGC707 (high quality)
Gene: Protein-coding gene on chromosome 11 (20,387,549 to 20,509,350, forward strand). Ensembl gene ENSG00000185238.
Subcellular location: Cytoplasm, cytosol; Nucleus
Pathways (Reactome):
Chromatin organization: RMTs methylate histone arginines
Metabolism of proteins: Protein methylation
Gene Ontology:
Molecular function: histone H4R3 methyltransferase activity; methyltransferase activity; protein binding; protein-arginine N-methyltransferase activity; protein-arginine omega-N asymmetric methyltransferase activity; protein-arginine omega-N monomethyltransferase activity
Biological process: negative regulation of protein ubiquitination; negative regulation of retinoic acid biosynthetic process; positive regulation of osteoblast differentiation; transcription initiation-coupled chromatin remodeling; ribosome biogenesis
Cellular component: cytoplasm; nucleus; cytosol
Genetic constraint (gnomAD): Loss-of-function variants: 40 observed, 44.6 expected, observed/expected ratio (o/e) 0.9, 90% interval 0.7 to 1.17. The upper end of that interval is the gene's LOEUF score, 1.17, which puts it in group 5 of 6, group 1 being the genes least tolerant of losing a copy. Missense variants: 528 observed, 515.53 expected, observed/expected ratio (o/e) 1.02, 90% interval 0.95 to 1.1. Synonymous variants: 169 observed, 183.58 expected, observed/expected ratio (o/e) 0.92, 90% interval 0.81 to 1.05.
Homologues: Orthologues: chimpanzee PRMT3 (99% identical), pig PRMT3 (94% identical), rabbit PRMT3 (93% identical), macaque PRMT3 (92% identical), guinea pig PRMT3 (92% identical), mouse Prmt3 (90% identical), rat Prmt3 (88% identical), dog PRMT3 (87% identical), tropical clawed frog prmt3 (62% identical), zebrafish prmt3 (59% identical), Drosophila melanogaster Art3 (37% identical), Drosophila melanogaster Art6 (23% identical), and 2 more. Paralogues in human: PRMT1 (32% identical), PRMT8 (31% identical), PRMT2 (24% identical), CARM1 (24% identical), PRMT6 (22% identical), PRMT9 (19% identical), PRMT7 (15% identical).
Diseases named in the same sentence as PRMT3 in open-access papers:
PRMT3 is named in the same sentence as 54 diseases in open-access papers, as found by Europe PMC text mining. Sharing a sentence is not in itself a finding about the gene and the disease. The quoted sentences say what the papers report.
hepatocellular carcinoma (10 papers, 2018 to 2025). A malignant tumor that arises from hepatocytes. "This study investigates the role of PRMT3 in PD-L1-associated tumor immunosuppression in hepatocellular carcinoma (HCC)." (PMID 40050608, 2025). "This dual functionality positions PRMT3 as a biomarker for predicting immunotherapy response and a therapeutic target in hepatocellular carcinoma." (PMID 41583428, 2025). "This crucial discovery positions PRMT3 not only as a biomarker for predicting responses to immunotherapy but also as a promising therapeutic target in the treatment of malignancies, such as hepatocellular carcinoma." (PMID 41583428, 2025). "• In hepatocellular carcinoma, SGC707 can inhibit the activity of PRMT3 and affect the methylation of LDHA by PRMT3; It can also block the enhancement of glycolysis induced by the overexpression of PRMT3." (PMID 41583428, 2025). "However, the role of protein arginine methyltransferase 3 (PRMT3) in hepatocellular carcinoma (HCC) remains unknown." (PMID 35090076, 2022). "Lei's research discovered significant upregulation of PRMT3 in hepatocellular carcinoma (HCC) and proved that PRMT3 facilitates glycolysis and HCC growth by enhancing arginine methylation of LDHA, serving as a potential biomarker for HCC patient prognosis." (PMID 39964832, 2025).
pancreatic cancer (9 papers, 2018 to 2025). "Elevated PRMT3 expression has been observed in various tumors and is linked to poor clinical outcomes, including in pancreatic cancer, glioblastoma, and HCC." (PMID 40050608, 2025). "In this study, we show that PRMT3 is upregulated in pancreatic cancer and is associated with poor patient survival, suggesting a novel oncogenic function of PRMT3." (PMID 31324208, 2019). "We found that the expression of PRMT3 is upregulated in pancreatic cancer, and its expression is associated with poor survival." (PMID 31324208, 2019). "Importantly, though the overexpression of PRMT3 has been detected in pancreatic cancer and is associated with chemoresistance, the role of PRMT3 in other human cancers still remains elusive to date." (PMID 35090076, 2022). "In pancreatic cancer, PRMT3 enhances chemoresistance by methylating heterogeneous nuclear ribonucleoprotein A1 (hnRNPA1), which stabilizes ABCG2 mRNA." (PMID 40050608, 2025). "Previous studies also demonstrated that PRMT3 was involved in tumor progression and therapy resistance in several cancer types, including colorectal cancer, pancreatic cancer, endometrial carcinoma, and glioblastoma." (PMID 39256398, 2024). "During the preparation of this study, the impact of PRMT3 on metabolic reprogramming in pancreatic cancer was revealed." (PMID 35090076, 2022). "PRMT3 has been shown to regulate metabolic reprogramming in pancreatic cancers by methylating glycolytic pathway components such as GAPDH and ABCG2 to reprogram cellular metabolism to promote tumor progression." (PMID 36351894, 2022). "Analysis of data retrieved from human protein atlas showed that liver and pancreatic cancer patients with high PRMT3 expression levels presented with worse overall survival times compared with patients with low expression level." (PMID 34753906, 2021). "To elucidate the biological function of PRMT3, we sought to identify its interacting proteins in pancreatic cancer cells." (PMID 31324208, 2019). "Ectopic expression of the R248 mutant in human L3.6pl pancreatic cancer cells, which express abundant endogenous PRMT3, also decreased the total GAPDH activity in cells." (PMID 31324208, 2019). "Our results indicate that R248 is the major residue methylated by PRMT3 in vivo, and R248 methylation enhances metabolic reprogramming and cellular proliferation of pancreatic cancer cells." (PMID 31324208, 2019). "The PRMT3 protein level of human pancreatic tumors was detected by immunoblotting and immunohistochemical staining." (PMID 31324208, 2019). "To verify the clinical significance of PRMT3, we compared the expression of PRMT3 in immortalized human pancreatic ductal epithelial (HPDE) cells and human pancreatic cancer cell lines and found that PRMT3 was upregulated in most of cancer cell lines." (PMID 31324208, 2019). "Overexpression of PRMT3 led to increased resistance to GEM in pancreatic cancer cells, whereas reduction of PRMT3 restored GEM sensitivity in resistant cells." (PMID 30577570, 2018). "Our previous study showed that epigenetic modifying enzymes including protein arginine methyltransferase 3 (PRMT3) are dysregulated in gemcitabine (GEM)-resistant pancreatic cancer cells." (PMID 30577570, 2018). "Together, these data suggested that upregulation of ABCG2 expression by PRMT3 contributes to GEM resistance in pancreatic cancer." (PMID 30577570, 2018). "In the study of drug resistance in pancreatic cancer, PRMT3 enhances chemotherapy resistance in pancreatic cancer by methylating the RNA recognition motif of heterogeneous nuclear ribonucleic acid protein 1, thereby increasing the expression of G-member 2 of the ATP-binding cassette subfamily." (PMID 38911125, 2024). "Because GAPDH is an important effector for PRMT3 to reprogram cellular metabolism, we hypothesized that PRMT3-overexpressing pancreatic cancer cells may be addicted to GAPDH for proliferation." (PMID 31324208, 2019).
pancreatic cancer (continued). "The clinical significance of PRMT3 in pancreatic cancer was studied by database analysis." (PMID 31324208, 2019). "In addition, the increase of PRMT3 was detected in 69% (11/16) of the pancreatic tumor tissues investigated." (PMID 31324208, 2019). "Our results suggest that inhibition of PRMT3 might be a therapeutic strategy to improve the GEM sensitivity in pancreatic cancer treatment." (PMID 30577570, 2018). "In this study, we show that PRMT3-mediated R248 methylation of GAPDH is critical for metabolic reprogramming and cellular proliferation, and double blockade of glycolysis and mitochondrial respiration could be a novel strategy for the treatment of PRMT3-overexpressing pancreatic cancer." (PMID 31324208, 2019). "Therefore, targeting PRMT3 may be a potential therapeutic approach for the treatment of GEM-resistant pancreatic cancer." (PMID 30577570, 2018). "In addition to GEM, PRMT3-overexpressing cancer cells also showed increased resistance to irinotecan, SN-38, and topotecan, indicating that upregulation of PRMT3 contributes to multidrug resistance in pancreatic cancer cells." (PMID 30577570, 2018). "Inhibition of PRMT3 could be a novel strategy for the treatment of GEM-resistant pancreatic cancer." (PMID 30577570, 2018). "A recent report showed that PRMT3-mediated methylation of glyceraldehyde-3-phosphate dehydrogenase (GAPDH) at R248 enhances its catalytic activity, thus increasing glycolysis in pancreatic cancer cells." (PMID 40050608, 2025). "Previous studies report that PRMT3 enhances chemoresistance by upregulating ABCG2 expression and by inducing metabolic reprogramming in pancreatic cancer." (PMID 34753906, 2021). "It would be worthwhile to further evaluate the combination of PRMT3 inhibitors and GEM as a treatment option for pancreatic cancer in vivo." (PMID 30577570, 2018). "In the current study, we attempt to further our understanding of the molecular mechanisms by which PRMT3 and PRMT6 modulate the GEM resistance in pancreatic cancer." (PMID 30577570, 2018). "In addition to PANC-1 cells, we also tested the effect of PRMT3 inhibition on the glycolysis and mitochondrial respiration in normal HPDE cells and L3.6pl and Capan-2 pancreatic cancer cells." (PMID 31324208, 2019). "In addition to EHMT2, we found that two other members of the PRMT family, PRMT3 and PRMT6, are highly upregulated in GEM-resistant pancreatic cancer cells." (PMID 30577570, 2018). "Our results suggest that PRMT3 mediates metabolic reprogramming and cellular proliferation through methylating R248 of GAPDH, and double blockade of GAPDH and mitochondrial respiration could be a novel strategy for the treatment of PRMT3-overexpressing pancreatic cancer." (PMID 31324208, 2019).
colorectal cancer (7 papers, 2021 to 2025). A primary or metastatic malignant neoplasm that affects the colon or rectum. "Collectively, these data robustly implicate high PRMT3 expression as a pivotal PTM driving chemoradiation resistance in advanced colorectal cancer, associating it with inferior prognosis and attenuated responsiveness to neoadjuvant chemoradiation regimens." (PMID 41147802, 2025). "reveal that in colorectal cancer, there is a significant elevation in PRMT3 expression levels, which correlates with patients' overall survival." (PMID 39964832, 2025). "In colorectal cancer, PRMT3 binds to HIF-1α and methylates its Arg803 residue, inhibiting HIF-1α’s ubiquitin-mediated degradation and activating glycolytic genes." (PMID 41583428, 2025). "In the context of colorectal cancer, PRMT3’s role in promoting immune evasion becomes even more pronounced." (PMID 41583428, 2025). "In colorectal cancer, PRMT3 promotes tumorigenesis through dual mechanisms whereby it stabilizes HIF1α and METTL14 in a methylation-dependent manner, thereby enhancing glycolysis, angiogenesis, and inflammation." (PMID 41583428, 2025). "Taken together, these results indicate that PRMT3 confers chemoradiation resistance of colorectal cancer in vivo and in vitro." (PMID 41147802, 2025). "To investigate the direct impact of PRMT3 on inducing chemoradiation resistance in colorectal cancer, we generated PRMT3‐KO SW480 and SW620 cell lines and the efficiency of PRMT3‐KO by two independent sgRNAs in the pooled cells was confirmed by Western blot." (PMID 41147802, 2025). "In summary, the findings of the current study show that PRMT3 was high expressed in colorectal cancer and the expression level was correlated with overall survival of patients." (PMID 34753906, 2021). "The findings indicate that PRMT3 is upregulated in colorectal cancer (CRC) tissues compared with adjacent normal tissue and its expression is negatively correlated with overall survival time of patients." (PMID 34753906, 2021). "IHC and RT-PCR assays were carried out to explore the expression level of PRMT3 in colorectal cancer." (PMID 34753906, 2021). "In colorectal cancer, PRMT3 promotes immune evasion through c-MYC stabilization." (PMID 41583428, 2025). "For example, methylation of HIF1α by PRMT3 could enhance angiogenesis and glycolysis, influencing colorectal cancer development; in glioblastoma, it might promote cell proliferation; and in breast cancer, assist in inducing apoptosis." (PMID 39964832, 2025). "Targeting the PRMT3-HIF1α axis through pharmacological inhibitors or methylation-blocking peptides may overcome anti-angiogenic resistance in colorectal cancer." (PMID 41583428, 2025).
endometrial cancer (7 papers, 2023 to 2025). Primary or metastatic malignant neoplasm involving the endometrium (mucous membrane that lines the endometrial cavity). "Functionally, PRMT3 inhibition sensitizes endometrial cancer cells to PD-1 blockade, cisplatin, and radiotherapy, highlighting PRMT3 as a novel therapeutic target that indirectly modulates METTL14 activity to enhance ferroptosis and immunotherapy efficacy." (PMID 41164187, 2025). "• SGC707 inhibits the activity of PRMT3, which enhances the sensitivity of endometrial cancer cells to iron death." (PMID 41583428, 2025). "In endometrial cancer (EC), protein arginine methyltransferase 3 (PRMT3)-mediated METTL14 promotes ferroptosis sensitivity by reducing the expression and stability of glutathione peroxidase 4 (GPX4)." (PMID 40823093, 2025). "It is noteworthy that blocking PRMT3 can improve the suppressive impact of cisplatin and radiation therapy on endometrial cancer." (PMID 39964832, 2025). "In endometrial cancer, PRMT3 interacts with the Arg418 residue of METTL14 and enhances METTL14’s m6A catalytic activity via methylation, thereby regulating ferroptosis-related genes." (PMID 41583428, 2025). "In endometrial carcinoma, PRMT3 drives malignant progression by methylating METTL14, reducing m6A modification of GPX4." (PMID 40050608, 2025). "Targeting PRMT3 with SGC707 treatment enhances oxaliplatin response in HCC, and combining SGC707 with anti-PD-1 therapy boosts antitumor effects in endometrial carcinoma." (PMID 40050608, 2025).
breast carcinoma (6 papers, 2023 to 2025). "The research further proved that PRMT3 acts as a crucial regulator of breast cancer cell proliferation and metastasis, both in vitro and in vivo." (PMID 39964832, 2025). "We then examined publicly available protein-protein interaction data in Biogrid33 and found that HSP60 was among the PRMT3 interactors identified by multiplex CF/MS in breast cancer cells." (PMID 39256398, 2024). "While studies of PRMT3 focus more on the control of apoptosis and tumor progression in breast cancer, its involvement in PDAC has been mainly associated with chemo-resistance, likely due to PRMT3-mediated metabolic reprograming of PDAC cells." (PMID 38612768, 2024). "This indicates that DAL‐1/4.1B and PRMT3 could be significant regulators of apoptosis in breast cancer cells." (PMID 39964832, 2025). "Mechanistically, PRMT3 regulates the endoplasmic reticulum (ER) stress signalling pathway by promoting asymmetric dimethylation of histone H4 arginine 3 (H4R3me2a), endowing breast cancer cells with robust proliferative and metastatic capabilities." (PMID 39964832, 2025). "Additionally, the study identified that small molecule inhibitors targeting PRMT3 activity could represent a promising method for breast cancer treatment, providing new avenues for the precise diagnosis and therapy of IMPC." (PMID 39964832, 2025). "Additionally, the data in GSE65194 showed that PRMT1, PRMT3, CARM1, PRMT5, and PRMT6 were highly expressed in basal-like breast cancer." (PMID 38476024, 2024).
liver cancer (6 papers, 2023 to 2025). An epithelial or non-epithelial malignant neoplasm that arises from the liver. "IGF2BP1 arginine methylation mediated by protein arginine methyltransferase 3 (PRMT3) promotes oxaliplatin resistance through stabilizing the mRNA of HEG1 in liver cancer." (PMID 40592832, 2025). "It is noteworthy that PD-1 antibody therapy in liver cancer can upregulate PRMT3 expression through the IFNγ-STAT1 pathway, forming a negative feedback loop that promotes immune resistance." (PMID 41154773, 2025). "Recent research has discovered that PRMT3 plays a crucial role in immune evasion in liver cancer." (PMID 41154773, 2025). "This positions PRMT3 overexpression as a potential biomarker for identifying oxaliplatin resistance in patients with liver cancer, linking higher PRMT3 levels to poorer outcomes and diminished therapeutic responses to oxaliplatin-based hepatic artery infusion chemotherapy (HAIC)." (PMID 38997696, 2024). "Recent research has shown that PRMT3 methylates IGF2BP1 at R452, contributing to oxaliplatin resistance in liver cancer patients." (PMID 40050608, 2025).
glioblastoma (4 papers, 2022 to 2025). The most malignant astrocytic tumor (WHO grade IV). "In glioblastoma, Lys acetylation of PRMT3 promotes nuclear translocation, leading to co-localization with nuclear HIF-1α and thus prioritizing HIF-1α methylation." (PMID 41583428, 2025). "PRMT3 has been shown to have an increased expression in patients with glioblastoma, with in vitro studies showing that PRMT3 expression is necessary for glioblastoma cell proliferation and invasive metastasis." (PMID 40869229, 2025). "To further determine the function of PRMT3 in patient-derived glioblastoma stem cells, we transduced GSC11 and GSC20 with lentiviral vectors carrying shRNAs to knockdown PRMT3." (PMID 36351894, 2022). "In glioblastoma (GBM), PRMT3-mediated stabilization of HIF1α drives angiogenesis and glycolysis under hypoxic conditions." (PMID 41583428, 2025). "In summary, PRMT3 and CARM1 are viewed as potential oncogenes, their overexpression significantly impacting a variety of cancers, such as colorectal, liver, pancreatic, prostate, endometrial, breast, ovarian, oral cancers, and glioblastomas." (PMID 39964832, 2025). "Knockdown of PRMT3 markedly reduced the proliferation and migration of GBM cell lines and patient-derived glioblastoma stem cells (GSC) in cell culture, while its over-expression increased the proliferative capacity of GSC cells by promoting cell cycle progression." (PMID 36351894, 2022).